DAB2IP (DAB2 interacting protein)
Diseases named in the same sentence as DAB2IP in open-access papers (continued):
Sharing a sentence is not in itself a finding about the gene and the disease.
tumor (continued). "Moreover, circRNA-5692 overexpression attenuated the EMT process and implanted HCC tumor growth in vivo by promoting demethylation in the DAB2IP gene." (PMID 31776329, 2019). "DAB2IP is a member of the disable gene family and exhibits tumor inhibitory activity." (PMID 30602706, 2018). "DAB2IP has recently been identified as a regulator of tumour growth and apoptosis." (PMID 27907910, 2017). "We further explored whether DAB2IP CpG1 methylation measurements may be affected by ITH by comparing results obtained from morphologically distinct regions of the same tumor." (PMID 27129174, 2016). "Moreover, DAB2IP stands for a promising direction for developing targeted therapies due to its capacity to inhibit tumor cell growth in vitro and in vivo." (PMID 26658103, 2016). "We have recently reported tumor suppressive role of DAB2IP in RCC development." (PMID 27129174, 2016). "Thus, DAB2IP functions as a signaling scaffold protein that coordinately regulates Ras and NF-κB through distinct domains to repress tumor growth and metastasis, respectively." (PMID 26658103, 2016). "In fact, we found relatively low variability of methylation measurements within individual tumor compared with the variability among different patient tumors, which further supports the potential of DAB2IP CpG1 methylation analysis for routine prognostic evaluation." (PMID 27129174, 2016). "Indeed, DAB2IP functions as a potent tumor suppressor by inhibiting tumor cells proliferation, epithelial-to-mesenchymal transition leading to cancer metastasis, and the appearance of cancer stem cell." (PMID 27129174, 2016). "With longer follow up and increased sample size, we hypothesized that pretreatment tumor status of DAB2IP would also predict worse malignancy‐specific survival (PCSS)." (PMID 26471467, 2015). "Future research may be directed toward creating molecularly based therapeutic strategies to upregulate DAB2IP and restore the tumor suppressor's presence within the neoplastic cells or by targeting downstream effectors." (PMID 26471467, 2015). "Potential clinical application is that in the future we may be able to effectively use tumor DAB2IP expression from a patient's biopsy specimen as a means of determining curability of their cancer with standard radiation‐based therapeutic regimens." (PMID 26471467, 2015). "Together, our results suggest that infiltrating T cells may promote RCC cell invasion via increasing the RCC cell ERβ expression to inhibit the tumor suppressor DAB2IP signals." (PMID 26587829, 2015). "The vivo results showed that DAB2IP was necessary for tumor growth and metastasis in CRC." (PMID 26336990, 2015). "Instead, we compared the tumor staining with the surrounding normal prostate tissue as the control to know whether the tumor retained normal DAB2IP expression or reduced the protein's expression." (PMID 26471467, 2015). "Tumor suppressors such as DAB2IP have been reported as EZH2 or PRC2 targets." (PMID 25537508, 2015). "Our data also demonstrate a tumor suppressive role of DAB2IP in CRC progression." (PMID 26336990, 2015). "DAB2IP is a putative tumor suppressor and member of the RAS‐GAP family." (PMID 26471467, 2015). "Pretreatment tumor DAB2IP status remained significant in multivariable analyses." (PMID 26471467, 2015). "Through interaction with various factors, DAB2IP can modulate the activities of various pathways including Ras-Raf-ERK, ASK1-JNK, and PI3K-Akt, through which loss of DAB2IP can deregulate survival and apoptosis pathways, leading to tumor development." (PMID 24912918, 2014). "DAB2IP is an emerging tumor suppressor, which is often epigenetically down-regulated in cancer." (PMID 24912918, 2014). "Therefore, our results indicate that phosphorylation at S847 of DAB2IP is important for its downstream effector functions, and thus regulation of the phosphorylation status at S847 is important for the tumor suppressor roles of DAB2IP." (PMID 24912918, 2014).
tumor (continued). "In addition to its tumor suppressor role, DAB2IP also plays an important role in regulating brain development." (PMID 24073285, 2013). "Furthermore, the IHC test indicated that administration of tRF‐34‐antagomir also suppressed the expression levels of Ki‐67, N‐cadherin, Vimentin, and CD34 protein levels and increased the expression levels of DAB2IP and E‐cadherin in the xenograft tumour tissues." (PMID 40263693, 2025). "Although we did not observe an increase in tumor nuclear localization of p65 with low DAB2IP, there was distinct stromal p65 cellular expression in patients with low DAB2IP displaying higher grades, potentially related to an altered tumor microenvironment for these tumors." (PMID 39418101, 2024). "Interestingly, evidences suggest that DAB2IP may respond to physical alterations of the tumor microenvironment (TME) and, consequently, modulate cell behavior upon mechanical stimuli." (PMID 38902547, 2024). "Therefore, targeting the mechanisms responsible of DAB2IP epigenetic silencing may be a valid strategy to re-establish its tumor-suppressive function in cancer." (PMID 38902547, 2024). "When DAB2IP-depleted cancer cells were xenografted in nude mice, the resulting tumors recruited abundant macrophages; strikingly, elimination of macrophages by treatment with liposomal clodronate suppressed tumor formation, establishing a key role for the infiltrate in this model." (PMID 38902547, 2024). "Therefore, the pharmacological reactivation of DAB2IP might be an innovative and feasible strategy to reduce tumor growth and dissemination, and improve the clinical response to primary chemotherapy treatments." (PMID 38902547, 2024). "Reduced expression of DAB2IP in neoplasm may indicate a poor prognosis of many malignant cancers." (PMID 26658103, 2016). "DAB2IP, as a novel tumor suppressor, could prevent RCC metastasis via inhibiting HIF-α." (PMID 26587829, 2015). "Indeed, wedelolactone could activate PRC2 downstream tumor suppression genes such as DAB2IP, ADRB2, CDKN2A and GADD45A, thus it serves as a mechanism for its inhibition on PRC2-dependent cancer cells." (PMID 25944687, 2015). "In addition to genetic event, our data indicate that DAB2IP, a novel family of RasGTPase-activating protein family as a potent tumor suppressor, is epigenetically silenced, which is suppressed by EZH2 and other epigenetic machinery such as DNA methylation and histone acetylation." (PMID 25115390, 2014). "All the data suggests that DAB2IP may function as a tumor suppressor gene." (PMID 22046421, 2011). "Specifically, LRP2 was significantly downregulated in RB compared to controls, whereas CUBN, DAB2IP, GIPC1, and CAV1 were significantly upregulated in tumor tissue." (PMID 41374987, 2025). "GIPC1 and DAB2IP, which regulate PI3K–AKT, ERK, and RhoA pathways, are predominantly reduced in dedifferentiated tumor subtypes, consistent with the release of growth-promoting signaling." (PMID 41374987, 2025). "While tumor-like cells showed low SRC, SRCIN1, and DAB2IP expression, SLA was predominantly expressed in these cells." (PMID 40917877, 2025). "Dab2IP, an Ras-GAP family member, functions as a tumor suppressor and modulates both the PI3K/AKT and MAPK pathways." (PMID 41010338, 2025). "Several of the genes that demonstrated a putative role as predictive biomarkers are either well-known tumor suppressors (RASSF1, XAF1, ASC/TMS1, ASPP1, DAB2IP) or DNA damage response regulators (SLFN11)." (PMID 39051186, 2024). "Surprisingly, multiple previously reported tumor suppressors of KIRC were found in these downregulated genes, including SOX6, DAPK1, PDZK1, TXNIP, DAB2IP, and CMTM4." (PMID 37737260, 2023). "The EZH2 protein mediates modifications in histone methylation that repress several tumor suppressor genes, as DKKI, CDH1, and DAB2IP." (PMID 37404760, 2023). "It was reported that DAB2IP was downregulated in HCC and played an important role in EMT process, tumor migration and invasion." (PMID 38015711, 2023).
tumor (continued). "DOC-2/DAB2 interactive protein (DAB2IP), a potential tumor suppressor, is often observed to be repressed by epigenetic silencing in a variety of malignant tumors." (PMID 34775484, 2022). "Further univariate Cox regression analysis identified WHO grade, tumor size, T status, N status, M status, CRT response and DAB2IP expression to have a significant impact on DSS (P = 0.012, 0.003, 0.001, 0.030, 0.022, < 0.001 and < 0.001 respectively)." (PMID 35248066, 2022). "The results showed that the expression of DAB2IP (P < 0.001), T status (P < 0.001), and CRT response (P = 0.004) were independent predictors of tumor prognosis." (PMID 35248066, 2022). "Based on H3K27me3-mediated gene expression silencing, EZH2 often functions as a transcriptional repressor to downregulate tumor suppressors such as ADRB2 and DAB2IP." (PMID 35059393, 2021). "Previous reports showed that EZH2 targets a cascade of tumour suppressors, such as CDX1, FOXC1, LATS2, CDH1 and DAB2IP." (PMID 33336896, 2021). "The xenograft assays also showed a cooperative effect on tumor formation of RASSF1A and DAB2IP suppression." (PMID 33348649, 2020). "Among the potential target genes of miRNA-328-5p, the DAB2IP, NFIC, IL-27, and HIC1 genes were tumor suppressors." (PMID 31776329, 2019). "Disabled homolog 2-interacting protein (DAB2IP), acts as a putative tumour suppressor gene, and it is downregulated by epigenetic modification in multiple aggressive cancers." (PMID 31666665, 2019). "DAB2IP (DOC2/DAB2 interactive protein) is downregulated in several cancer types, and its downregulation is involved in tumor cell proliferation, apoptosis, metastasis, and epithelial-mesenchymal transition (EMT)." (PMID 29743885, 2018). "DOC-2/DAB2 interactive protein (DAB2IP) is frequently lost in high-grade PCa and has been recognized as a potent tumor suppressor in PCa progression." (PMID 28642840, 2017). "For example, the tumor suppressive gene, DAB2 interacting protein (DAB2IP) was inhibited by EZH2/PRC2." (PMID 28264478, 2017). "Surprisingly, other tumor-suppressor genes, such as PTCH1, DAB2IP, and WT1 were included in the gained regions." (PMID 27481518, 2016). "Previous studies have demonstrated EZH2 can decrease DAB2IP expression and E2 can increase EZH2 through ERs and tumor progression." (PMID 26587829, 2015). "This resulted in the up-regulation of EZH2-silenced tumor suppressor genes, including CDKN1C, DAB2IP, and WNT5a, in a dose-dependent manner in multiple cancer cell lines (e.g., T24, MBT2, and PC3)." (PMID 25431950, 2014). "Among them, 10 genes have been reported in HCC, and ZMYND10, SYK, DAB2IP, and DLEC1 have been reported to be tumor-suppressor genes in HCC." (PMID 21625442, 2011). "However, notable protein-mRNA discordances emerged for CUBN, CAV1, DAB2IP, and GIPC1, which showed transcriptional upregulation in GSE208143 despite protein-level downregulation in most tumor subtypes." (PMID 41374987, 2025). "More importantly, in our rescue experiments, we demonstrated that the overexpression of DAB2IP significantly mitigated the effects of the tRF‐34‐P4R8YP9LON4VHM mimics on the HCC cells proliferation, migration, invasion, and tumour cell‐induced angiogenic properties." (PMID 40263693, 2025). "Also, we identified novel predicted tumor-suppressive ligands (SLIT3, DCN, CCN3, THBS1, INHA and INHBA), proteins (DNASE1L3, SULF1, PTEN, OAS1, and DAB2IP), and receptors (P2RX4, CDHR2, PTPRJ, and PTPRH) in MSC1 cells." (PMID 40564222, 2025). "Our data on RB are consistent with this mechanism, as reduced DAB2IP may relieve the inhibition of PI3K–AKT/ERK signaling, thereby supporting tumor growth." (PMID 41374987, 2025). "Mechanically, DAB2IP interacted with the E3 ubiquitin ligase STUB1 via its PER domain, thus triggering STUB1 mediated HIF-1α ubiquitylation and degradation, and inhibit glucose metabolism and tumor progression." (PMID 38862467, 2024).
tumor (continued). "Epigenetic drugs are inevitably non-specific, but alternative approaches can be developed to increase expression of a tumor-suppressor gene such as DAB2IP that is silenced but not deleted in cancer." (PMID 38902547, 2024). "However, miR-1307 is involved in tumor development by influencing target genes, such as Forkhead box O3a (FOXO3A), SET And MYND Domain Containing 4 (SMYD4) and Disabled homolog 2-interacting protein (DAB2IP), to further promote cancer invasion." (PMID 37889117, 2023). "We detected three transcripts of DAB2IP and discovered that only the mRNA expression of Transcript 1 was decreased in BC tissues compared to tumour‐adjacent noncancerous tissues." (PMID 36536485, 2022). "Interestingly, DAB2IP expression correlated closely with World Health Organization (WHO) grade (P < 0.001), Tumor size (P < 0.001), T status (P = 0.003), Node (N) status (P < 0.001), and distant lymph node metastasis (M) status (P = 0.017)." (PMID 35248066, 2022). "Using Tumour‐sphere culture, our data showed that inhibition of self‐renewal in TNBC spheroids by DAC treatment could be attenuated by DAB2IP‐inhibition." (PMID 36536485, 2022). "IHC assay showed that tumour tissues exhibited more intense DAB2IP staining comparing to tumour adjacent noncancerous tissues." (PMID 36536485, 2022). "Previous studies demonstrated that miR-889 could regulate the tumor cellular behaviors by targeting serval target genes, such as KLF9, SIX1, DAB2IP, TAB1, FGFR2, TWEAK." (PMID 34116691, 2021). "Additionally, DAB2IP, which belongs to the Ras‐GTPase activating protein (RAS‐gap) family, exhibits tumour suppressor activity." (PMID 33166004, 2021). "Given the fact that DAB2IP has Ras GAP homology domain, it is not surprising that DAB2IP appears to be a tumor suppressor gene since RasGAPs' role includes promoting GTPase inactivation and is often inactivated in cancers." (PMID 26658103, 2016). "DAB2IP, a member of the RAS‐GAP protein family, is a novel and putative tumor suppressor." (PMID 26471467, 2015). "In summary, we demonstrated a reciprocal regulation between DAB2IP, a tumor suppressor, and Skp2, an oncogenic protein, in normal prostatic epithelia and PCa cells, which represents paradigm shift of signalosome pattern in normal cell to malignant tumor." (PMID 25115390, 2014). "However, comparison of the tumor-adjacent gastric tissue between HP+ and HP- patients revealed 8 differentially methylated CpG sites located within 7 genes (CCNA1, CSPG2, DAB2IP, DIO3, FLT1, STAT5A and TWIST1)." (PMID 24674026, 2014). "DAB2IP can inhibit cell survival by suppressing the phosphatidyl inositol 3-kinase (PI3K)-Akt kinase signaling pathway and can also promote tumor necrosis factors mediated apoptosis by activating the apoptosis signal–regulating kinase (ASK1)-c-Jun N-terminal kinase (JNK) pathway." (PMID 24073285, 2013). "Another interesting point is that a significant tumor-suppressive effect could be obtained by increasing DAB2IP levels not only in cancer cells but also in non-transformed cells of the tumor microenvironment, in particular endothelial cells." (PMID 38902547, 2024). "DOC2/DAB2 interaction protein (DAB2IP; also known as apoptosis signal‐regulating kinase 1‐interacting protein‐1 [AIP1]) directly interacts with DOC‐2/DAB2 to regulate various pathological characteristics of tumour cells, such as proliferation, invasion and apoptosis." (PMID 33166004, 2021). "In multiple solid tumors, DAB2IP is clearly downregulated and its expression levels negatively correlate with tumor growth, angiogenesis, lymph node metastasis, advanced clinical stage, and resistance to therapies, establishing it function as a tumor suppressor." (PMID 38902547, 2024).
cancer (56 papers, 2005 to 2025). A tumor composed of atypical neoplastic, often pleomorphic cells that invade other tissues. "The loss of DAB2IP function represents an advantage for cancer initiation and progression, and accordingly, it is frequently downregulated in various human malignancies." (PMID 40867592, 2025). "DAB2IP is rarely mutated in cancer but is frequently downregulated or inactivated by multiple mechanisms." (PMID 40867592, 2025). "In the following years additional evidences confirmed that DAB2IP loss contributes to resistance to chemo- and radio-therapy of multiple different cancers." (PMID 38902547, 2024). "Mechanistically, DAB2IP interacts with RAC1 and impedes RAC1-mediated β-catenin nuclear translocation, so that DAB2IP loss promotes the induction of cancer stem cell phenotypes and DOC resistance." (PMID 38902547, 2024). "We also reviewed evidences that treatments that restore endogenous DAB2IP levels or functions in cancer cells inhibit oncogenic features associated to its loss of activity." (PMID 38902547, 2024). "In this regard, we identified a candidate set of NF-κB target genes differentially expressed between DAB2IP-low and -high Luminal A tumors that are associated with aggressive cancers, including some involved in RNA splicing." (PMID 39418101, 2024). "The loss of ATM is sufficient to restore the sensitivity of DAB2IP-silenced cancer cells to radiotherapy by delaying double‐strand break (DSB) repair kinetics and counteracting the activation of NF-κB and p38MAPK." (PMID 38902547, 2024). "A previous study indicated that DAB2IP is a cancer suppressor; and loss of DAB2IP triggers EMT and distant metastasis in BC." (PMID 36536485, 2022). "Particularly, downregulation of DAB2IP expression was reported to be associated with resistance to chemo or radio therapy and worse outcome in several types of human cancers." (PMID 35248066, 2022). "Recently, several studies revealed that the loss of DAB2IP expression is associated with therapeutic resistance in cancer cells." (PMID 34775484, 2022). "Loss of DAB2IP expression promotes PCa development and confers resistance to radiation-induced apoptosis, thus inducing a cancer stemness phenotype." (PMID 30602706, 2018). "The loss of DAB2IP expression allows PCa cells to proliferate, enhances their anti-apoptotic potential, and develops a cancer stemness phenotype, which confers resistance to radiation-induced apoptosis." (PMID 28081154, 2017). "We identified proline-rich transmembrane protein 2 (PRRT2) and DAB2 interacting protein (DAB2IP) to be frequently mutated in all different cancer cell line types." (PMID 27907910, 2017). "Secondly, as a member of the Ras GTPase-activating family, DAB2IP has been implicated in the invasion in different types of cancers such as prostate, endometrial, breast, lung, hepatocellular and gastrointestinal cancers, etc.." (PMID 29163762, 2017). "The aberrant alteration of DAB2IP in cancer is caused by a variety of mechanisms, including the aberrant promoter methylation, histone deacetylation, and others." (PMID 26658103, 2016). "Interestingly, the genes more highly expressed in DAB2IP-low tumors also displayed enrichment of NF-κB signaling pathway genes, along with genes regulating a canonical hallmark of cancer progression, namely epithelial-to-mesenchymal transition (EMT)." (PMID 39418101, 2024). "By day 7 of cell plating, DAB2IP knockdown spheroids had lost organization and compactness in the cancer cells, thereby supporting the hypothesis that loss of DAB2IP promotes an aggressive tumorigenic phenotype." (PMID 39418101, 2024). "Here, we review the most recent publications concerning the impact of DAB2IP loss-of-function in tumors, focusing on strategies that may be adopted to counteract its inhibition in cancer." (PMID 38902547, 2024). "Silencing of DAB2IP caused by promoter hypermethylation has been implicated in several cancers." (PMID 36536485, 2022).